EZH2 (enhancer of zeste 2 polycomb repressive complex 2 subunit)
Diseases named in the same sentence as EZH2 in open-access papers (continued):
Sharing a sentence is not in itself a finding about the gene and the disease.
prostate carcinoma (continued). "Given that neither TOP2A nor EZH2 commonly harbor somatic changes in prostate cancer that can be detected by DNA sequencing, this highlights the potential of 5hmC-seq to add to current analyses of cfDNA in advanced cancers." (PMID 36251389, 2022). "The synthesis of N-Myc/AR/EZH2-PRC2 complex is notably dependent on the presence of EZH2, and N-MYC shows a remarkable synergistic effect with EZH2 and AR to inhibit AR signaling by methylation, leading to neuroendocrine transformation of prostate cancer." (PMID 35633416, 2022). "Notwithstanding its canonical role as a transcriptional silencer, EZH2 has several non-canonical functions in prostate cancer, which complicate therapeutic attempts to target it." (PMID 36212399, 2022). "Of note, EZH2 also contributes to the expression of AR transcriptional signatures in models of both primary prostate cancer and CRPC via a different mechanism that is independent of both PRC2 and its methyltransferase activity." (PMID 36212399, 2022). "One study showed that the oncogenic function of EZH2 in cells of castration-resistant prostate cancer is independent of PRC2-mediated transcriptional repression." (PMID 36612203, 2022). "This alteration of EZH2 activity by ASCL1 was not unique to prostate cancer, but seems like a common effect of ASCL1 as observed in lung adenocarcinoma and SCLC." (PMID 35477723, 2022). "For example, EZH2 functions in prostate cancer cells in a manner independent of other PRC2 subunits, surprisingly acting as a transcriptional activator." (PMID 33804165, 2021). "EZH2 activation can promote expansion of breast tumor initiating cells, whereas GSK126, the novel EZH2 inhibitor, exerts anticancer effects on gastric cancer and prostate cancer by inhibiting cell migration, invasion and angiogenesis." (PMID 33879635, 2021). "On the other hand, the enhancer of zeste homolog 2 (EZH2) component of the polycomb 2 complex determines K180 tri-methylation, which is essential for maintaining STAT3 phosphorylation and transcriptional activity in glioblastoma and prostate cancer cells." (PMID 34642818, 2021). "In prostate cancer (PCa) cells, a group of genes related to glucose metabolism such as those of the key glycolytic enzyme HK2, GLUT1, and ribosomal protein S6 kinase B1 (RPS6KB1) are positively correlated with the expression of EZH2." (PMID 32448308, 2020). "In addition, the tumorigenicity of cancer stem cells was found to be promoted by EZH2 via the binding and methylation of STAT3 in glioblastoma and in a model of prostate cancer." (PMID 33163485, 2020). "Moreover, combined treatment with the USP7-specific inhibitorP5091 and EZH2 inhibitors, such as GSK126, EPZ6438, and DZNep, inducedsynergistic inhibitory effects on cell migration, invasion, and sphere-formingpotential in prostate cancer cells." (PMID 32453339, 2020). "Here, we found that NTN3 transcription is positively regulated by both EZH2 and AR in prostate cancer (r = 0.2297 and 0.2863, respectively), suggesting that NTN3 may play a oncogenic role in prostate cancer." (PMID 32251318, 2020). "Further, an oncogenic function of EZH2 in prostate cancer, independent of its role as a transcriptional repressor, was also reported." (PMID 32155117, 2020). "After treating prostate cancer cells with each EZH2 inhibitor incombination with or without P5091, we assessed the cell proliferation,migration, invasion, and sphere-forming abilities." (PMID 32453339, 2020). "For example, histone methyltransferase EZH2, a core unit of PRC2 complex, can play a PRC2-independent role by interacting with androgen receptor (AR) to activate a subset of its target genes in an androgen-independent prostate cancer cell line." (PMID 32093739, 2020). "Despite the important role of EZH2 in prostate cancer development, the downstream genes, and pathways mediating EZH2 oncogenic effect are still not fully revealed, impeding the development of targeted therapeutics." (PMID 31636385, 2020).
prostate carcinoma (continued). "Oncomining of previously reported RNA-seq data generated from prostate cancer clinical specimens 46 showed that EZH2 expression negatively correlated with FOXO1 at the mRNA level in a cohort containing both primary and metastasis prostate cancers (r = - 0.55; P = 1e-8)." (PMID 31410199, 2019). "In addition, EZH2 expression negatively correlates with FOXO1 protein level in both cultured cancer cell lines and prostate cancer patient specimens." (PMID 31410199, 2019). "Interestingly, other studies have shown that the EZH2 inhibitor GSK126 in combination with Enzalutamide synergistically inhibits cell proliferation and induces apoptosis of enzalutamide-resistant prostate cancer cells." (PMID 31366128, 2019). "Interestingly, EZH2 and BRCA1 are coregulated in primary prostate cancer cells and cooperate in the regulation of CSC phenotype and properties." (PMID 31366128, 2019). "In such a context, the catalytic component of PRC2, the methyltransferase enhancer of Zeste homolog 2 (EZH2), another HSP90 client protein, is upregulated in several tumors, including breast and prostate cancers, and its overexpression correlates with a poor prognosis." (PMID 31163702, 2019). "On the other hand, miR-101 was reported to inhibit tumor aggressiveness through targeting EZH2 which is an epigenetic regulator of cell survival, proliferation, CSC phenotype and function, in various cancers including endometrial cancer prostate cancer, pancreatic cancer." (PMID 29534065, 2018). "To further characterize the link between CREB and EZH2 activation in patient samples, we measured the levels of H3K27me3 and CREB activation (by pS133-CREB) in a tissue microarray (TM) with 78 cases of human prostate cancer and normal samples." (PMID 30287808, 2018). "At advanced stages of prostate cancer progression, EZH2 can acquire an oncogenic function which is independent of its polycomb-associated transcriptional repressor activity as in CRPC cells." (PMID 30651935, 2018). "Together, these results indicate that the CREB/EZH2/TSP1 pathway is responsive to ADT-induced CREB activation in mouse xenografts of prostate cancer cells, and CREB signaling is critical for castration-induced EZH2 activation, angiogenesis, and NE phenotypes in vivo." (PMID 30287808, 2018). "Several EZH2 inhibitors have entered clinical trials, but not for the indication of prostate cancer." (PMID 28486411, 2017). "In chemotherapy-resistant prostate cancer, MALAT1 was shown to directly interact with EZH2 protein, suggesting that MALAT1 may play a key role as an RNA cofactor of EZH2 and that the EZH2-MALAT1 association may be a new therapeutic target." (PMID 28412742, 2017). "Moreover, a direct relationship between EZH2 and TIMP2/3-tissue inhibitors of metalloproteinase-results in enhanced proteolytic activity of MMP-9 in prostate cancer cells." (PMID 28410242, 2017). "Moreover, MUC1-C was necessary for EZH2 expression in DU145 prostate cancer cells, supporting the notion that MUC1-C drives the upregulation of EZH2 in diverse types of cancer cells." (PMID 28785086, 2017). "Beside its repressive role, EZH2 also acts independently of the PRC2 complex and co-activates gene transcription by interacting with transcription factors such as the AR, making it a promising target for prostate cancer treatment." (PMID 28486411, 2017). "The topoisomerase IIa (TopIIa) inhibitor etoposide 42 combined with the Enhancer of Zeste Homologous 2 (EZH2) inhibitors 7-deazaneplanocin A (DZNep) 43 or GSK126 44 induces cell death in murine and human prostate cancer cell lines and showed therapeutic efficacy in vivo." (PMID 27752293, 2016). "Consistently, in several solid tumors (such as prostate cancer, ovarian cancer and lung cancer), CDKN1A/p21 and CDKN1B/p27 were identified as EZH2 targets by ChIP-qPCR analysis, and inhibited due to elevated level of EZH2." (PMID 27998273, 2016).
prostate carcinoma (continued). "Both EZH2 and MALAT1 are highly expressed in human prostate cancers, especially metastatic CRPC." (PMID 26516927, 2015). "This is partly reflected in the TCGA expression profile where the expression of other PRC1/2 complex proteins does not change to the extent as compared to EZH2 in normal prostate and prostate cancer." (PMID 25115397, 2014). "Interestingly, ADRB2 is also a target gene of two important markers in prostate cancer that are involved in transcriptional regulation; v-ets avian erythroblastosis virus E26 oncogene homolog (ERG) and Enhancer of zeste homolog 2 (EZH2)." (PMID 25629002, 2014). "Thus increased EZH2 expression and its subsequent recruitment appears to be the primary mechanism involved in epigenetic silencing of ID4 in prostate cancer." (PMID 25115397, 2014). "We transfected PC-3 cells with the negative control or EZH2 targeting siRNAs and treated the cells with docetaxel, a drug used clinically to treat prostate cancer." (PMID 25341040, 2014). "ID4 expressing (LNCaP) and non-expressing (DU145 and C81) prostate cancer cell lines were used to investigate EZH2, H3K27me3 and DNMT1 enrichment on ID4 promoter by Chromatin immuno-precipitation (ChIP)." (PMID 25115397, 2014). "We analyzed miR-205, EZH2, and miR-31 expression in eight pairs of human prostate cancer specimens and the adjacent non-malignant tissues using real-time PCR." (PMID 25341040, 2014). "SiRNA knockdown of EZH2 increased miR-31 expression and decreased the antiapoptotic protein E2F6 (E2F transcription factor 6) (a target of miR-31), resulting in the sensitization of prostate cancer cells to docetaxel-induced apoptosis." (PMID 25341040, 2014). "While enhanced EZH2 expression in prostate cancer biopsies has independent prognostic value, there is no consensus yet on cutoff points in clinical practice." (PMID 25243131, 2014). "Also this study revealed that reverse correlation of RAR beta 2, ER alpha, PGR, and RGMA expressions with EZH2, SRC3, and AR expressions in prostate cancer tissues suggests that these genes are the target of EZH2." (PMID 25535400, 2014). "Moreover, the results showed that mRNA level of EZH2, AR and SRC3 are upregulated in prostate cancer compared to normal prostate tissues and this correlates positively with Gleason score, PSA levels and clinical stages." (PMID 25535400, 2014). "However, treatment for prostate cancer cells with SAHA, a potent histone deacetylase (HDAC) inhibitor, results in depletion of EZH2 and induction of RAR beta 2 in prostate cancer cell lines." (PMID 25535400, 2014). "In this study, the focus will be on histone modifications and the primary objectives are to map H3K27me3 marks and quantify RAR beta 2, ER alpha, SRC3, RGMA, PGR, and EZH2 gene expressions in prostate cancer tissues compared to normal tissues." (PMID 25535400, 2014). "EZH2 is a target of ERG, and therefore overexpressed in TMPRSS2:ERG-positive prostate cancers." (PMID 25496077, 2014). "Finally, recent data suggests that EZH2 regulated by STAT3 is correlated to the pathological stage and progression of prostate cancer." (PMID 24772452, 2013). "To further clarify whether EZH2 and BMI1 participated in HOXB13 transcriptional repression in DU145 prostate cancer cells, we constructed EZH2 siRNA and BMI1 siRNA plasmids and transfected them into DU145 cells, respectively." (PMID 22808286, 2012). "We found that high levels of EZH2 expression during cancer progression induce repression of TIMP genes (TIMP2 and TIMP3), leading to increased activity of MMP-9 and thus to increased invasive activity of prostate cancer cells." (PMID 22272343, 2012). "It was very interesting to identify EZH2 and SMYD3 as the most significantly changed and overexpressed histone modifiers in prostate cancer, since the two modifications are antagonistic and correspond to repressive (H3K27me3) and active (H3K4me3) gene transcription, respectively." (PMID 19262738, 2009).
prostate carcinoma (continued). "Although full functional role of this association is not yet understood, Ezh2 and SIRT1 both are highly expressed in prostate cancer and are associated with prostate cancer progression (and our unpublished data)." (PMID 21566744, 2008). "We show that in 22Rv1 prostate cancer cells, EZH2 occupies a large set of gene loci lacking H3K27me3, and these non-canonical genomic sites are instead co-occupied by p300, RNA Polymerase II and BRD4 and are rich in histone marks associated with transcriptional activation." (PMID 40534232, 2025). "The histone methyltransferase EZH2, the catalytic subunit of Polycomb repressive complex 2 (PRC2), inhibits the transcription of downstream target genes mainly by methylation of H3K27, and it has been shown to be significantly overexpressed in NEPC compared to other prostate cancer clinical samples." (PMID 38391963, 2024). "Moreover, in prostate cancer, it was found that genomic amplification in the region Ch 7q31-36 could result in downregulating CAV1, while overexpressing EZH2." (PMID 36471782, 2022). "However, the oncogenic function of EZH2 in cells of castration-resistant prostate cancer seems to be independent of PRC2-mediated transcriptional repression." (PMID 36612203, 2022). "Finally, 5hmC sequencing of cell-free DNA from patients with metastatic disease proved useful as a prognostic biomarker able to identify an aggressive subtype of prostate cancer using the genes TOP2A and EZH2, previously only detectable by transcriptomic analysis of solid tumor biopsies." (PMID 36251389, 2022). "Here in this study, we find that the tumor suppressor HNF1B is repressed by EZH2 in prostate cancer cell lines, and functions together with RBBP7 in suppressing EMT through down-regulation of SLUG expression, which expands our knowledge of how EZH2 is involved in this deleterious disease." (PMID 31636385, 2020). "Additionally, MYC and ETS transcription factors in prostate cancer, NF-YA in epithelial ovarian cancer, and STAT3 in colorectal cancer regulate EZH2 expression, while the fusion oncoprotein EWS-FLI1 induces EZH2 expression in Ewing’s sarcoma." (PMID 33003334, 2020). "To confirm previous findings, we analyzed the microarray data of GSE21032, GSE16560, and GSE35988, and found that the EZH2 mRNA levels in metastatic prostate cancer samples were much higher compared with those of the nonmetastatic prostate cancer samples and the paired normal tissues." (PMID 31636385, 2020). "However, the role of USP7 in themodulation of EZH2 protein stability in prostate cancer cells has not yet beenelucidated." (PMID 32453339, 2020). "Interestingly, TSP1 was among a list of genes identified as potential EZH2 repressed targets in prostate cancer cells, with no further validation." (PMID 30287808, 2018). "However, the exact functional role of EZH2-mediated epigenetic silencing of tumor suppressive miRNAs in prostate cancer progression has not been systematically studied." (PMID 29141691, 2017). "However, other non-enzymatic transcriptional activator functions of EzH2 have been observed in some triple negative breast and prostate cancers." (PMID 29285251, 2017). "Notably, miR-26a and miR-138a block the G1/S-phase transition in prostate cancer, independent of EZH2, via a concerted inhibition of crucial cell cycle regulators." (PMID 28410242, 2017). "Because EZH2 is an important target in prostate cancer, our results suggest that knockdown of DANCR could strengthen the effect of EZH2 inhibitor on the suppression of prostate cancer metastasis." (PMID 27191265, 2016). "Moreover, we determined whether DNACR regulated cell invasion synergistically with EZH2 and whether DANCR affected the effect of androgen-AR signaling and enzalutamide, an inhibitor of AR, on migration and invasion of prostate cancer cells." (PMID 27191265, 2016). "Thus, in the context of c-Myc-induced prostate cancer, cell proliferation and malignant evolution appear unaffected by the absence of Ezh2." (PMID 26637281, 2015).
prostate carcinoma (continued). "In addition, the oncogenic role of EZH2 in castration-resistant prostate cancer was found independent of PRC2 complex." (PMID 26038315, 2015). "A recent report has shown that the oncogenic function of EZH2 in cells of CR prostate cancer is independent of its role as a transcriptional repressor and involves its the ability to act as a coactivator for critical transcription factors including the androgen receptor." (PMID 24353195, 2013). "Although this pattern of overexpressed EZH2 and depressed SLIT2 is observed in other cancer types, the combination of these two may serve as a pertinent duo-panel of characteristic biomarkers for prostate cancer prognosis." (PMID 22641253, 2012). "Furthermore, our ChIP assays revealed that EZH2 was able to directly bind onto the HOXB13 promoter, and this may be a silencing mechanism of HOXB13 in the DU145 malignant prostate cancer cells." (PMID 22808286, 2012). "Hence, we hypothesized that Myc may be a key driver of EZH2 overexpression in PIN and prostate cancer lesions via repression of miR-26a and miR-26b." (PMID 21941025, 2011). "Furthermore, EZH2 and SUZ12 interact with N-MYC through MB III in castration-resistant prostate carcinoma (CRPC), leading to abrogation of androgen receptor signaling and consequently driving progression to neuroendocrine prostate cancer (NEPC), the aggressive subgroup of late-stage prostate cancer." (PMID 28505071, 2017). "They discovered that this molecule reduced but did not fully suppress EZH2 expression in DU145 and PC3 human prostate carcinoma cell lines." (PMID 35327559, 2022). "Neither gene is frequently altered by copy number changes in mCRPC; EZH2 had DNA alterations in 0.5% of 1465 samples, while TOP2A is not commonly included in prostate cancer targeted panels." (PMID 36251389, 2022). "Our Western blot analysis of cell lysates revealed the global levels of EZH2-mediated H3K27me3 and H1.2 much higher in MCF7 breast, LD611 bladder and LNCaP prostate cancer cells than in their nontransformed cells (MCF10-2A, LD419, and MLC)." (PMID 26581166, 2015). "Noticeably, treatment of AR− prostate cancer cells with ATRA did not change the expressions of HOXB13, EZH2 and DNMT3b at mRNA level, implicating a different mechanism of ATRA action in this particular cell background." (PMID 22808286, 2012). "To investigate further the transcriptional repression of TIMP3 expression by EZH2, we quantitatively determined TIMP3 mRNA and protein levels in three prostate cancer cell lines (LNCaP, PC3, and DU145) with and without knockdown of EZH2 expression." (PMID 22272343, 2012). "EZH2 reactivity was observed in three out of ten HCC patients, one out of five colorectal cancer patients and in none of the prostate cancer samples." (PMID 17024127, 2006). "However, this study also provides one mechanistic explanation for why EZH2 and HDAC inhibitors are not effective as single agents in prostate cancer." (PMID 37104245, 2023). "In the genes of the MEmagenta module, we found that the known genes closely related to cancer stemness in non-prostate cancer, such as BRCA1, EZH2, FOXM1, CDC20, and CDCA8, were all clustered in this module, indicating these genes were also closely related to the stemness of prostate cancer cells." (PMID 33985534, 2021). "Whether EZH2 overexpression is also regulated by other mechanisms in PIN and primary prostate cancer lesions has not previously been examined." (PMID 21941025, 2011). "Thus, it is conceivable that EZH2 inhibitor can reverse EZH2-mediated repression of FOXO1 expression in both PTEN positive and negative prostate cancer cells; however, it induces substantial death only in PTEN-positive cells where FOXO1 protein is primarily located in the nucleus." (PMID 31410199, 2019).